B3GNT2 (UDP-GlcNAc:betaGal beta-1,3-N-acetylglucosaminyltransferase 2)
Description:
Beta-1,3-N-acetylglucosaminyltransferase involved in the synthesis of poly-N-acetyllactosamine. Catalyzes the initiation and elongation of poly-N-acetyllactosamine chains. Shows a marked preference for Gal(beta1-4)Glc(NAc)-based acceptors. Probably constitutes the main polylactosamine synthase.
Synonyms: Beta3Gn-T1; BGnT-2; Beta3Gn-T2; B3GNT1; B3GNT-2; BETA3GNT; B3GN-T2; B3GN-T1; 3-Gn-T1; 3-Gn-T2; B3GNT; BGNT2; beta-1
Tractability: Small molecule: a structure with a bound ligand is known. Antibody: UniProt predicts a signal peptide or a membrane-spanning region. PROTAC: ubiquitination databases record sites on it.
Target class: Enzyme; Transferase
Gene: Protein-coding gene on chromosome 2 (62,195,485 to 62,224,731, forward strand). Ensembl gene ENSG00000170340.
Subcellular location: Golgi apparatus membrane
Subcellular location (Human Protein Atlas): Vesicles
Pathways (Reactome):
Metabolism: Keratan sulfate biosynthesis
Metabolism of proteins: O-linked glycosylation of mucins
Gene Ontology:
Molecular function: N-acetyllactosaminide beta-1,3-N-acetylglucosaminyltransferase activity; protein binding; hexosyltransferase activity
Biological process: poly-N-acetyllactosamine biosynthetic process; keratan sulfate proteoglycan biosynthetic process; carbohydrate derivative metabolic process; glycoprotein biosynthetic process
Cellular component: Golgi membrane; membrane
Genetic constraint (gnomAD): Loss-of-function variants: 12 observed, 28.88 expected, observed/expected ratio (o/e) 0.42, 90% interval 0.26 to 0.67. The upper end of that interval is the gene's LOEUF score, 0.67, which puts it in group 2 of 6, group 1 being the genes least tolerant of losing a copy. Missense variants: 413 observed, 514.66 expected, observed/expected ratio (o/e) 0.8, 90% interval 0.74 to 0.87. Synonymous variants: 192 observed, 200.31 expected, observed/expected ratio (o/e) 0.96, 90% interval 0.85 to 1.08.
Homologues: Orthologues: chimpanzee B3GNT2 (100% identical), macaque B3GNT2 (98% identical), rabbit B3GNT2 (92% identical), dog B3GNT2 (92% identical), pig B3GNT2 (91% identical), guinea pig B3GNT2 (91% identical), rat B3gnt2 (88% identical), mouse B3gnt2 (87% identical), tropical clawed frog b3gnt2 (68% identical), zebrafish b3gnt2b (57% identical), zebrafish b3gnt2a (55% identical), Drosophila melanogaster brn (22% identical), and 3 more. Paralogues in human: B3GNT9 (35% identical), B3GNT4 (34% identical), B3GNT7 (34% identical), B3GNT3 (33% identical), B3GNT6 (33% identical), B3GNT8 (31% identical), B3GNT5 (25% identical), B3GALT2 (25% identical), B3GALT1 (24% identical), B3GALT5 (21% identical), B3GALNT1 (20% identical), B3GALT9 (20% identical), and 3 more.
Diseases named in the same sentence as B3GNT2 in open-access papers:
B3GNT2 is named in the same sentence as 30 diseases in open-access papers, as found by Europe PMC text mining. Sharing a sentence is not in itself a finding about the gene and the disease. The quoted sentences say what the papers report.
psoriasis (5 papers, 2014 to 2025). An autoimmune condition characterized by red, well-delineated plaques with silvery scales that are usually on the extensor surfaces and scalp. "In patients with psoriasis and rheumatoid, there is a decrease in B3GNT2 gene activity, linking B3GNT2 to various autoimmune disorders." (PMID 40736072, 2025). "Genes co-expressed with B3GNT2 in macrophages were located next to intergenic sequences with elevated density of motifs recognized by TFs important to psoriasis pathogenesis, such as IRF1, STAT4 and STAT5 (Part B)." (PMID 24885462, 2014). "Furthermore, this study marks the initial identification of several proteins—MAPRE1, SWAP70, VPS26A, BRD2, and B3GNT2—as potentially contributing factors in the pathogenesis of psoriasis." (PMID 39883516, 2024).
melanoma (4 papers, 2018 to 2023). A malignant, usually aggressive tumor composed of atypical, neoplastic melanocytes. "Upregulation of B3GNT2, which encodes a poly-N-acetyllactosamine synthase, allows human melanoma cells to evade T cell killing in different cancer cell types, and can reduce T cell activation and disrupt the interaction between tumor and T cells." (PMID 36407095, 2022). "Our screen identifies four candidate genes (CD274 (PD-L1), MCL1, JUNB, and B3GNT2) that, upon upregulation, enable human melanoma cells to evade T cell killing in diverse cancer cell types and mouse xenografts." (PMID 35338135, 2022). "To predict the prognosis of melanoma patients, we calculated the risk score of each patient based on the expression and corresponding lambda value of seven genes (PLA2G2D, FUT8, PLA2G4E, PLA2G5, PLA2G1B, B3GNT2, and ST3GAL5)." (PMID 37205993, 2023).
ankylosing spondylitis (3 papers, 2021 to 2025). An autoimmune chronic inflammatory disorder characterized by inflammation in the vertebral joints of the spine and sacroiliac joints. "Latest research on ankylosing spondylitis (AS) indicates a link between the B3GNT2, PSMG1 genes and susceptibility to AS among western populations." (PMID 40736072, 2025). "B3GNT2, GPR35, and PSMG1genes are related to ankylosing spondylitis in the Chinese Han population." (PMID 40736072, 2025).
autoimmune disease (3 papers, 2021 to 2025). A disorder resulting from loss of function or tissue destruction of an organ or multiple organs, arising from humoral or cellular immune responses of the individual to their own tissue constituents. "GWAS have shown that SNPs reducing the expression of B3GNT2 are associated with autoimmune diseases, including RA and AS." (PMID 40002719, 2025). "Our results show that miR-3687 binds to the mRNA of the B3GNT2 gene, which is associated with autoimmune diseases." (PMID 39049823, 2024).
colon cancer (2 papers, 2016 to 2022). "Some scholars validate that there are enriched mutations in B3GNT2 genes in colon cancer." (PMID 35444644, 2022).
colorectal cancer (2 papers, 2018 to 2021). A primary or metastatic malignant neoplasm that affects the colon or rectum. "However, whether β3GnT8 and β3GnT2 play a role in colorectal cancer and, if so, the underlying mechanisms remain unclear." (PMID 29875690, 2018). "Together, these results illustrate that the novel role and the molecular mechanism of β3GnT8 and β3GnT2 in promotion of colorectal cancer invasion." (PMID 29875690, 2018). "We found that overexpression of β3GnT8 and β3GnT2 promoted invasion of colorectal cancer cells, whereas knockdown of β3GnT8 and β3GnT2 inhibited the invasive activity." (PMID 29875690, 2018). "However, the expression of β3GnT2 was decreased in colorectal cancer tissues, which was contrary to the β3GnT8 expression." (PMID 29875690, 2018). "As expected that expression of β3GnT2 also significantly elevated the mRNA levels of CD147, galectin 3, and MMPs in colorectal cancer cells in comparison with the controls." (PMID 29875690, 2018). "Mechanistically, β3GnT8 and β3GnT2 regulated the expression of HG-CD147 and the level of polylactosamines in colorectal cancer cells." (PMID 29875690, 2018). "The expression of β3GnT8 and β3GnT2 was not positively correlated in clinical colorectal cancer tissues, while β3GnT8 worked as a coordinator with β3GnT2 to regulate the expression of polylactosamine and MMPs in vitro." (PMID 29875690, 2018).
hepatocellular carcinoma (2 papers, 2022 to 2023). A malignant tumor that arises from hepatocytes. "In addition, there are reports stating that β3GnT2, a polylactosamine synthase, regulates glycosylation of EGFR in human hepatocellular carcinoma cells." (PMID 35393406, 2022).
adenomyosis (1 paper, 2025). The growth of endometrial tissue inside the muscular wall of the uterine corpus. "Likewise, B3GNT2 has been shown to impair cell-cell interaction and reduce T cell activation in tumor, raising the possibility of a potential role in dampening immune surveillance in adenomyosis." (PMID 41356013, 2025). "At the molecular level, several enzymes involved in keratan sulfate biosynthesis were consistently upregulated in eutopic endometrium from adenomyosis patients, including B4GALT1, B3GNT2, CHST1, and CHST6." (PMID 41356013, 2025).
amyotrophic lateral sclerosis (1 paper, 2024). Amyotrophic lateral sclerosis (ALS) is a neurodegenerative disease characterized by progressive muscular paralysis reflecting degeneration of motor neurons in the primary motor cortex, corticospinal tracts, brainstem and spinal cord. "For instance, FN1 and SIK3 are associated with spondyloepiphyseal dysplasia, PADI2 is related to sclerosis, ERBB4 is connected to amyotrophic lateral sclerosis (ALS), and B3GNT2 and BACE1 are associated with muscular dystrophy and muscular inflammation, respectively." (PMID 38788487, 2024).
arterial disease (1 paper, 2022). "For example, B3GNT2 (UDP‐GlcNAc:BetaGal Beta‐1,3‐N‐Acetylglucosaminyltransferase 2) has been identified as up‐regulated in patients with arterial disease while CF significantly down‐regulated its expression." (PMID 35094491, 2022).
colorectal adenocarcinoma (1 paper, 2022). The most common type of colorectal carcinoma. "We found that these ten ligands and receptors had increased presence of poly-LacNAc at baseline in SW1417 colorectal adenocarcinoma cells, which express higher levels of endogenous B3GNT2 than A375 cells." (PMID 35338135, 2022).
esophageal carcinoma (1 paper, 2022). A primary or metastatic malignant neoplasm involving the esophagus. "However, the biological function and regulatory mechanism of β3GNT2 in esophageal carcinoma (ESCA) is still poorly understood." (PMID 35073841, 2022).
migraine (1 paper, 2022). "Among the identified 36 blood proteins with pleiotropic effects on migraine at SNPs within LD-independent loci, five proteins have two or more pleiotropic SNPs with migraine, including four SNPs for ERBB3, three SNPs for F2R, and two SNPs for B3GNT2, VEGFA and SCARF2." (PMID 35546551, 2022).
ovarian tumor (1 paper, 2023). "We observed 24 ABH antigen synthesis‐related genes in which five genes (FUT1, FUT2, FUT3, B3GNT3, and B3GNT2) were up‐regulated and three genes (ST3GAL3, ST3GAL4, and B3GALT2) were down‐regulated in ovarian tumor tissue versus adjacent tissues in all samples." (PMID 36415180, 2023).
parasite infection (1 paper, 2009). "In addition to strong expression of IFNβ and CCL5 in all cell types, parasite infection induces the expression of genes involved in cell-matrix interactions (osteopontin; SPP1) carbohydrate modification (B4GT5 and B3GNT2), vesicular transport SYTL3 and T-SNARE1 and Ca2+ homeostasis STIM1 and CARKL." (PMID 19480704, 2009).
cancer (11 papers, 2016 to 2025). A tumor composed of atypical neoplastic, often pleomorphic cells that invade other tissues. "B3GNT2/5 genes encoding β3GnT enzyme, one of the critical glycosyltransferases involved in this process has been shown to be associated with cancer cell migration, invasion, and metastasis in cancers, however, β3GnT7 enzyme decreases cancer cell motility and invasion." (PMID 31273306, 2019). "By examining patient tumor samples from TCGA, we found that expression of B3GNT2 was significantly higher than matched normal samples for 9 out of 31 types of cancer." (PMID 35338135, 2022). "Overexpression of four top candidate genes (CD274 (PD-L1), MCL1, JUNB, and B3GNT2) conferred resistance in diverse cancer cell types and mouse xenografts." (PMID 35338135, 2022). "The three mutations identified (R6X, P186T, and D247H) significantly alter B3GNT2 subcellular location or impair enzymatic activity and consequently enhance the migratory potential of cancer cells, observed in biochemical and cell assays." (PMID 33158990, 2021). "We found that β3GNT2 expression was increased in most types of cancers." (PMID 35073841, 2022). "Moreover, a recent study identified several potential cancer cell receptor targets for B3GnT2 and additionally showed reduced interaction between some ligands and receptors between tumour and T-cells upon overexpression of B3GnT2." (PMID 36980204, 2023). "The effects of MCL1 and B3GNT2 overexpression could be generalized to six and seven of the additional cell lines respectively, demonstrating the broad applicability of these candidate genes to other cancer types and supporting the patient tumor analyses." (PMID 35338135, 2022). "β1,3-N-acetylglucosaminyltransferase (β3GnT8) and β3GnT2 are key enzymes that catalyzes the formation of polylactosamine glycan structures by transferring GlcNAc to tetra-antennary β1-6-branched N-glycan and it also has an important effect on the progression of various types of human cancer." (PMID 29875690, 2018). "Considering B3GnT2 has recently been reported to modify several ligands and receptors that alter T-cell activation via interaction with cancer cells, there may be a more general role for B3GnT2 in the regulation of cancer-relevant signalling events, such as Wnt/β-catenin signalling." (PMID 36980204, 2023). "B3GNT2 is upregulated in T cells on activation, and a recent CRISPR screen showed evidence that this enzyme is important in modulating T cell activation in the setting of cancer." (PMID 37388915, 2023). "Although CPXM1, CCL4, ZBTB10 and B3GNT2 have not been reported to be related to the prognosis of ALL, the four genes we screened are all closely related to cancer, and we have reason to believe that they may also be potential genes for predicting the prognosis of ALL." (PMID 36407095, 2022).
tumor (10 papers, 2016 to 2025). "By analyzing the pathological features, we found that β3GNT2 expression was associated with the tumor size and TNM stage." (PMID 35073841, 2022). "We find that B3GNT2, encoding a poly-N-acetyllactosamine synthase, operates in an orthogonal pathway to target >10 ligands and receptors to disrupt interactions between tumor and T cells and reduce T cell activation." (PMID 35338135, 2022). "β3GNT2 expression was closely associated with the tumor size, TNM stage, and overall survival of ESCA patients." (PMID 35073841, 2022). "B3GNT2 encodes a poly-N-acetyllactosamine synthase that targets >10 ligands and receptors to disrupt interactions between tumor and T cells and reduce T cell activation." (PMID 35338135, 2022). "In vitro assays and xenograft tumor models were utilized to evaluate the impact of β3GNT2 on ESCA progression." (PMID 35073841, 2022). "We discovered that β3GNT2 knockdown suppressed tumor growth, as manifested by reduced tumor size, tumor weight, and tumor volume." (PMID 35073841, 2022). "B3GNT2 promotes resistance through an orthogonal pathway by increasing poly-LacNAc on at least ten tumor ligands and receptors to reduce T cell activation, highlighting the importance of poly-LacNAc in immuno-oncology." (PMID 35338135, 2022). "Focal copy number gain of MCL1 and B3GNT2 occurred more frequently than losses across tumor types (in 95 and 81% of total cases respectively)." (PMID 35338135, 2022). "By contrast, B3GNT2 overexpression produces higher resistance against T cells expressing TCR than CAR because B3GNT2 confers resistance by disrupting interactions between tumor and T cells to reduce T cell activation." (PMID 35338135, 2022). "Then we analyzed the protein levels of those tumor-related genes, and found that both β3GnT8 and β3GnT2 could markedly elevate MMP2 and MMP14 expression." (PMID 29875690, 2018). "β3GNT2 knockdown inhibited ESCA growth, migration, and invasion in vitro, as well as tumor formation in vivo." (PMID 35073841, 2022). "FUT1, FUT2, B3GNT2, GCNT2, and ST8SIA5 are involved in the blood group biosynthesis, a synthesis of blood group antigens process, which are glycan structures on cell surfaces that can influence tumour cell interactions with the TME, including immune system components." (PMID 39457550, 2024). "Our TCGA analysis suggests that increases in both the expression of B3GNT2 as well as copy number of MCL1 and B3GNT2 may generally promote tumor initiation or progression in the absence of immunotherapy." (PMID 35338135, 2022). "Together, these results suggest that increased expression of MCL1 and B3GNT2 may promote tumor progression and immune evasion in patients, whereas JUNB is not as clinically relevant across diverse tumor types." (PMID 35338135, 2022).
neurodegenerative disease (1 paper, 2024). A disorder of the central nervous system characterized by gradual and progressive loss of neural tissue and neurologic function. "As shown by the program results DE miR-3687, miR-612, miR-4261, miR-504-3p, miR-126-5p,and miR-411-5p bind to the mRNA of the B3GNT2, CSMD2, ATN1, CREBBP, ATXN1, EMIN4, and EFNA5 genes, which are associated with neurodegenerative diseases." (PMID 39049823, 2024).
B3GNT2 also shares sentences with these, for which no sentence is quoted: rheumatoid arthritis (4 papers); Graves disease (2); breast carcinoma (1); colon adenocarcinoma (1); Crohn disease (1); demyelinating disorders (1); infection (1); muscular dystrophy (1); osteoporosis (1); schizophrenia (1); spondyloepiphyseal dysplasia (1); virus infection (1).